SLCO1B1 (solute carrier organic anion transporter family member 1B1)
Description:
Mediates the Na(+)-independent uptake of organic anions. Shows broad substrate specificity, can transport both organic anions such as bile acid taurocholate (cholyltaurine) and conjugated steroids (dehydroepiandrosterone 3-sulfate, 17-beta-glucuronosyl estradiol, and estrone 3-sulfate), as well as eicosanoids (prostaglandin E2, thromboxane B2, leukotriene C4, and leukotriene E4), and thyroid hormones (T4/L-thyroxine, and T3/3,3',5'-triiodo-L-thyronine). Can take up bilirubin glucuronides from plasma into the liver, contributing to the detoxification-enhancing liver-blood shuttling loop. Involved in the clearance of endogenous and exogenous substrates from the liver. Transports coproporphyrin I and III, by-products of heme synthesis, and may be involved in their hepatic disposition. May contribute to regulate the transport of organic compounds in testes across the blood-testis-barrier (Probable). Can transport HMG-CoA reductase inhibitors (also known as statins), such as pravastatin and pitavastatin, a clinically important class of hypolipidemic drugs. May play an important role in plasma and tissue distribution of the structurally diverse chemotherapeutic drug methotrexate. May also transport antihypertension agents, such as the angiotensin-converting enzyme (ACE) inhibitor prodrug enalapril, and the highly selective angiotensin II AT1-receptor antagonist valsartan, in the liver. Shows a pH-sensitive substrate specificity towards prostaglandin E2 and T4 which may be ascribed to the protonation state of the binding site and leads to a stimulation of substrate transport in an acidic microenvironment. Hydrogencarbonate/HCO3(-) acts as the probable counteranion that exchanges for organic anions.
Synonyms: LST-1; OATP1B1; OATP2; OATPC; SLC21A6; OATP-C; HBLRR
Tractability: Small molecule: a structure with a bound ligand is known; a high-quality ligand is known; it belongs to a druggable protein family. Antibody: UniProt places it where antibodies can reach, with high confidence; its Gene Ontology location is reachable by antibodies, with high confidence; UniProt predicts a signal peptide or a membrane-spanning region; the Human Protein Atlas places it where antibodies can reach. PROTAC: its protein half-life has been measured; a small molecule that binds it is known.
Target class: Electrochemical transporter; SLC superfamily of solute carriers; SLC21/SLCO family of organic anion transporting polypeptides; Transporter
Safety:
Unwanted effects reported when the protein is acted on. In parentheses: how it was acted on, where the effect was seen, and who reports it.
adverse drug reaction (source: ClinPGx)
adverse events (source: ClinPGx)
atorvastatin-related myopathy (source: ClinPGx)
cerivastatin-related rhabdomyolysis (source: ClinPGx)
chemotherapy-induced amenorrhea (source: ClinPGx)
cough (source: ClinPGx)
creatine kinase levels (source: ClinPGx)
creatine kinase levels and adverse events in response to treatment (source: ClinPGx)
Diarrhea (source: ClinPGx)
drug toxicity (source: ClinPGx)
fluvastatin-related myopathy (source: ClinPGx)
GI toxicity (source: ClinPGx)
intolerance (source: ClinPGx)
lovastatin-related myopathy (source: ClinPGx)
myopathy (source: ClinPGx)
neutropenia (source: ClinPGx)
pravastatin-related myopathy (source: ClinPGx)
require glucarpidase treatment (source: ClinPGx)
rifampin-induced liver injury (source: ClinPGx)
rosuvastatin-related myopathy (source: ClinPGx)
simvastatin-related myopathy (source: ClinPGx)
statin-related myopathy or myalgia (source: ClinPGx)
Thrombocytopenia (source: ClinPGx)
toxic liver disease (source: ClinPGx)
Gene: Protein-coding gene on chromosome 12 (21,131,120 to 21,241,074, forward strand). Ensembl gene ENSG00000134538.
Subcellular location: Basolateral cell membrane; Basal cell membrane
Subcellular location (Human Protein Atlas): Plasma membrane
Pathways (Reactome):
Metabolism: Heme degradation; Recycling of bile acids and salts
Disease: Defective SLCO1B1 causes hyperbilirubinemia, Rotor type (HBLRR)
Drug ADME: Atorvastatin ADME
Transport of small molecules: Organic anion transport by SLCO transporters
Gene Ontology:
Molecular function: prostaglandin transmembrane transporter activity; protein binding; transmembrane transporter activity; bile acid transmembrane transporter activity; secondary active transmembrane transporter activity; thyroid hormone transmembrane transporter activity
Biological process: bile acid and bile salt transport; heme catabolic process; sodium-independent organic anion transport; transmembrane transport; xenobiotic metabolic process; prostaglandin transport; thyroid hormone transport
Cellular component: basal plasma membrane; basolateral plasma membrane; plasma membrane; membrane
Genetic constraint (gnomAD): Loss-of-function variants: 46 observed, 41.29 expected, observed/expected ratio (o/e) 1.11, 90% interval 0.88 to 1.42. The upper end of that interval is the gene's LOEUF score, 1.42, which puts it in group 5 of 6, group 1 being the genes least tolerant of losing a copy. Missense variants: 580 observed, 551.89 expected, observed/expected ratio (o/e) 1.05, 90% interval 0.98 to 1.13. Synonymous variants: 192 observed, 188.31 expected, observed/expected ratio (o/e) 1.02, 90% interval 0.91 to 1.15.
Homologues: Orthologues: chimpanzee SLCO1B1 (98% identical), dog SLCO1B2 (69% identical), mouse Slco1b2 (64% identical), rat Slco1b2 (63% identical), tropical clawed frog slco1b3 (44% identical), Drosophila melanogaster Oatp30B (29% identical). Paralogues in human: SLCO1B3 (80% identical), SLCO1C1 (44% identical), SLCO1A2 (39% identical), SLCO3A1 (31% identical), SLCO2B1 (30% identical), SLCO5A1 (29% identical), SLCO2A1 (28% identical), SLCO4C1 (27% identical), SLCO4A1 (25% identical), SLCO6A1 (22% identical).
Diseases named in the same sentence as SLCO1B1 in open-access papers:
SLCO1B1 is named in the same sentence as 155 diseases in open-access papers, as found by Europe PMC text mining. Sharing a sentence is not in itself a finding about the gene and the disease. The quoted sentences say what the papers report.
Hyperbilirubinemia (33 papers, 2013 to 2026). An increased amount of bilirubin in the blood. "In this study, the correlation between hyperbilirubinemia and two genes, SLCO1B1 and UGT1A1 variants were investigated in Thai neonates." (PMID 35501760, 2022). "This study aims to explore the correlation of the genetic variant of the two genes, UGT1A1 and SLCO1B1 causing hyperbilirubinemia in Thai newborns." (PMID 35501760, 2022). "In SLCO1B1 521 T > C variant, there was a significant correlation between hyperbilirubinemia and SLCO1B1 521 T > C (P = 0.041)." (PMID 35501760, 2022). "The rs4149056 variant of the SLCO1B1 gene was recently found to be associated with the risk of neonatal hyperbilirubinemia." (PMID 32796590, 2020). "A novel founding is that variant c.521T > C in SLCO1B1 is closely related to bilirubin levels and significantly increases the risk of unconjugated hyperbilirubinemia (OR = 2.54, 95% CI: 1.27–5.11, P = 0.009)." (PMID 31737051, 2019). "Our results indicate that variants of UGT1A1 and/or SLCO1B1 have combined effects on Chinese adult mild unconjugated hyperbilirubinemia." (PMID 31737051, 2019). "Based on previous studies, there is an association between SLCO1B1 with racial variety in regard to the severity of unconjugated neonatal hyperbilirubinemia." (PMID 31253110, 2019). "Rotor syndrome, a rare autosomal-recessive genetic disorder characterized by conjugated hyperbilirubinemia, is caused by biallelic pathogenic variants in both SLCO1B1 and SLCO1B3 genes." (PMID 32082363, 2019). "Further, SLCO1B1 variations c.388G > A (p.N130D, rs2306283) and c.521T > C (p.V174A, rs4149056) were also found to be risk factors for neonatal unconjugated hyperbilirubinemia." (PMID 31737051, 2019). "Aside from UGT1A1, variants of SLCO1B1 have also been known to contribute to the severity of neonatal hyperbilirubinemia in Asian populations." (PMID 31253110, 2019). "Specifically, variant c.521T > C within SLCO1B1 was found to have a significantly increased risk of hyperbilirubinemia (OR = 2.544, 95% CI: 1.267–5.11, P = 0.009)." (PMID 31737051, 2019). "Rotor syndrome is characterized by defective reuptake of BDG from the blood into the liver by OATP1B1/OATP1B3, encoded by SLCO1B1/1B3 and is known as a predominantly conjugated hyperbilirubinemia." (PMID 29259555, 2017). "The likelihood of developing neonatal hyperbilirubinemia was 1.55 times higher in infants with the A allele in SLCO1B1 388 G > A than in infants with the G allele (95% CI, 1.16–2.06)." (PMID 24090270, 2013). "Our study revealed that the 388 G > A mutation of the SLCO1B1 gene is associated with neonatal hyperbilirubinemia in Chinese neonates." (PMID 24090270, 2013). "The risk of neonatal hyperbilirubinemia was higher in SLCO1B1 388 G > A allele carriers (A/A + G⁄A) than in G⁄G allele carriers (RR, 1.50; 95% CI, 1.13–2.00)." (PMID 24090270, 2013). "No adverse events such as elevated MTX concentration, ALT elevation, hyperbilirubinemia, or prognosis were statistically correlated to two polymorphisms in SLCO1B1 (rs11045879 and rs4149056)." (PMID 24386571, 2013). "Our case-control study found that the variant SLCO1B1 388 G > A is associated with neonatal hyperbilirubinemia in Chinese neonates; further prospective cohort study is need to conform the association." (PMID 24090270, 2013). "Various factors are involved in the development of neonatal hyperbilirubinemia, including the SLCO1B1 gene, which requires further investigation as SLCO1B1 encodes a liver-specific member of the organic anion transporter family." (PMID 24090270, 2013). "Genetic analyses suggest that such cases of unconjugated hyperbilirubinemia could be linked to polymorphisms in SLCO1B1 and SCLO1B3." (PMID 31737051, 2019). "Therefore, this study provides valuable insight into the association of genetic factors especially SLCO1B1 with the severity of neonatal hyperbilirubinemia in Indonesia." (PMID 31253110, 2019).
Hyperbilirubinemia (continued). "Neonatal hyperbilirubinemia is more frequent and more severe in Chinese than in Europeans and Americans, and the SLCO1B1 mutation may explain the variability in the prevalence of neonatal hyperbilirubinemia among different ethnic groups." (PMID 24090270, 2013). "The genetics of racial differences might explain the different association between the genetic polymorphism of SLCO1B1 and neonatal hyperbilirubinemia among different ethnic groups." (PMID 24090270, 2013). "Recently, studies have suggested that variations of 388 G > A, 521 T > C, 463 C > A of the SLCO1B1 gene may predispose subjects to neonatal hyperbilirubinemia by limiting hepatic bilirubin uptake." (PMID 24090270, 2013). "Therefore, we conducted a case-control study of three variants (388 G > A, 521 T > C, 463 C > A) of SLCO1B1 and investigated their association with neonatal hyperbilirubinemia in the Chinese neonates." (PMID 24090270, 2013). "We hypothesized that the SLCO1B1 mutation may be one of the risk factors for neonatal hyperbilirubinemia, which possibly accounts for the variability in prevalence rates in the Chinese neonates." (PMID 24090270, 2013). "Additionally, it has also been demonstrated that SLCO1B1 polymorphisms, particularly the *5/*5 genotype, may be associated with an increased risk for statin-induced myopathy and hyperbilirubinemia." (PMID 39859305, 2025). "It is caused by pathogenic mutations in both SLCO1B1 and SLCO1B3 genes, and characterized by predominantly conjugated hyperbilirubinemia." (PMID 40901525, 2025). "Most studies highlight genetic polymorphisms as the cause to hyperbilirubinaemia, mostly with mutations involving UGT1A1 and SLCO1B1." (PMID 39609276, 2024). "Among the other 6 SNPs in the other 4 bilirubin metabolism genes, only rs2306283 in SLCO1B1 and rs2117032 in SLCO1B3 showed a suggestive association with neonatal hyperbilirubinemia risk." (PMID 26146841, 2015). "The study revealed that SLCO1B1 388 G > A occurred significantly more frequently in neonates with hyperbilirubinemia than in controls (RR = 1.50; 95% CI: 1.13–2.00)." (PMID 24090270, 2013). "The combined of SLCO1B1 was significantly related to severe hyperbilirubinemia (P = 0.041)." (PMID 35501760, 2022). "Therefore, this study aims to explore the correlation between two genes, UGT1A1 and SLCO1B1, and hyperbilirubinemia in Thai neonates." (PMID 35501760, 2022). "Moreover, SLCO1B1 combination was significant differences between the hyperbilirubinemia and the control group (P = 0.041)." (PMID 35501760, 2022). "In addition, other gene variants – including heme oxygenase (HO)-1, hepatic solute carrier organic anion transporter 1B1 (SLCO1B1), and UDP-glucuronosyltransferase 1A1 (UGT1A1)—have been reported as risk factors of neonatal hyperbilirubinemia." (PMID 27557546, 2016). "In addition, the SLCO1B1 and SLCO1B3 polymorphisms also contributed to an increased risk of hyperbilirubinemia." (PMID 26146841, 2015). "Interestingly, simultaneous homozygous mutations in SLCO1B1 and SLCO1B3, resulting in disruption of hepatic reuptake of bilirubin, may account for the predominantly conjugated hyperbilirubinemia of Rotor syndrome." (PMID 31737051, 2019). "Since there has been no report on SLCO1B1 polymorphism in relation with hyperbilirubinemia in Indonesia, this study aims to explore incidence of SLCO1B1*1B polymorphism in Indonesia based on 3 hospitals from different provinces and population, and their association with hyperbilirubinemia severity." (PMID 31253110, 2019). "Our study was also limited to only two genes, SLCO1B1 and UGT1A1, so other genes related with hyperbilirubinemia could be investigated in further studies." (PMID 35501760, 2022). "In contrast, the other 3 gene variants – including alpha thalassemia, blood group incompatibility, and SLCO1B1—are not related to hyperbilirubinemia." (PMID 27557546, 2016). "None of the haplotypes of SLCO1B1 and SLCO1B3 was found to be associated with hyperbilirubinemia." (PMID 38279097, 2024).
breast cancer (16 papers, 2011 to 2025). A primary or metastatic malignant neoplasm involving the breast. "SLCO1B1 polymorphisms influence the estrogenic response to aromatase inhibitor treatment in breast cancer." (PMID 35874705, 2022). "In a nested case-control study in the California Teachers Study cohort, only genetic variation in SLCO1B1 was associated with breast cancer risk." (PMID 27234217, 2016). "Patient age and SLCO1B1*5 allele variants predict the likelihood of young women with breast cancer developing CIA." (PMID 27234217, 2016). "When examining by HT use, we observed a strong association between several SNPs in SLCO1B1 and postmenopausal breast cancer risk in current EPT users." (PMID 21457551, 2011). "There was some evidence that, of these, rs4149013 in SLCO1B1 was associated with breast cancer risk in postmenopausal women (OR 1.39, 95% CI 1.07 to 1.81; uncorrected P = 0.015)." (PMID 21457551, 2011). "In this case-control study nested within the California Teachers Study cohort, genetic variation in only 1 (SLCO1B1) of 24 genes in the hormone metabolism pathway genes was associated with breast cancer risk." (PMID 21457551, 2011). "For postmenopausal women, 10 SNPs in SLCO1B1 were associated with breast cancer risk with an uncorrected P value of less than 0.01." (PMID 21457551, 2011). "We found evidence that genetic variation in SLCO1B1 is associated with breast cancer risk in postmenopausal women, particularly among those using EPT." (PMID 21457551, 2011). "SLCO1B1, a gene involved in the hepatic uptake of female sex steroids, seemed to be associated with breast cancer risk among postmenopausal women." (PMID 21457551, 2011). "In postmenopausal women who were using combined estrogen-progestin therapy (EPT) at cohort enrollment, the OR of breast cancer was 2.31 (95% CI = 1.47-3.62) per minor allele of rs4149013 in SLCO1B1 (P = 0.0003; within-gene PACT = 0.002; overall PACT = 0.023)." (PMID 21457551, 2011). "There was also an indication that estrogen-progestin therapy (EPT) may interact with SNPs in SLCO1B1; one variant (rs4149013) was significantly associated with breast cancer risk in EPT users." (PMID 27234217, 2016). "We found that rs4149013, a SNP located near the 5’ end of SLCO1B1 with unknown functional significance, was associated with breast cancer risk, and this association was restricted to EPT users (odds ratio (OR) = 2.3 per minor allele)." (PMID 25499601, 2014). "Ten of 38 tagging SNPs of SLCO1B1 showed significant associations with postmenopausal breast cancer risk; 5 SNPs (rs11045777, rs11045773, rs16923519, rs4149057, rs11045884) remained statistically significant after adjusting for multiple testing within this gene (PACT = 0.019-0.046)." (PMID 21457551, 2011). "Common genetic variations in SLCO1B1 may be associated with breast cancer risk in postmenopausal women, particularly in EPT users." (PMID 21457551, 2011). "However, there was also an indication that EPT may interact with SNPs in SLCO1B1; one variant in SLCO1B1 (rs4149013) was statistically significantly associated with breast cancer risk in EPT users." (PMID 21457551, 2011). "One Study have shown that SLCO1B1 variation can be used as a biomarker of breast cancer response to simvastatin." (PMID 34522968, 2021). "More recently, using an independent data from a breast cancer case-control study nested within CTS, our group reported that EPT use modified the effect of SLCO1B1 SNPs on breast cancer risk." (PMID 25499601, 2014). "However, our findings and those of CGEMS, combined with the previous literature on the role of this gene in affecting estrone absorption, suggest that further investigation of the role of SLCO1B1 genetic variation and its interaction with EPT on breast cancer risk is warranted." (PMID 21457551, 2011). "Despite previously published reports, SLCO1B3, SLCO2B1, and SLCO1B1 were not highly expressed in our breast cancer samples." (PMID 21625523, 2011).